BRCA2 (BRCA2 DNA repair associated)
Diseases named in the same sentence as BRCA2 in open-access papers (continued):
Sharing a sentence is not in itself a finding about the gene and the disease.
cancer (continued). "Carcinomas from three patients (Patients E, O and P), including a patient with homozygous frameshift mutation in BRCA2 (Patient P), had relatively low HRD scores (< 10) and low genome-wide LOH burden (<0.10)." (PMID 25916844, 2015). "The advantages of clinical testing include the possibility for close monitoring for pancreatic, as well as other BRCA2 mutation-associated cancers (breast, ovarian, prostate) in carriers." (PMID 24624093, 2014). "For example, PARP inhibitors have been shown to induce synthetic lethality to cancer cells with BRCA1 or BRCA2 mutations." (PMID 24465681, 2014). "This genomic instability provided by such mechanisms probably underlies the cancer predisposition caused by loss-of-function mutations in BRCA1 or BRCA2." (PMID 25594033, 2014). "Cancers occur when heterozygous individuals experience a somatic loss of heterozygosity event at the BRCA1 or BRCA2 locus, leaving only the abnormal allele intact." (PMID 25011685, 2014). "BRCA1 and BRCA2 germline mutations are the fundamental defect in hereditary OC where the normal allele of the carrier is inactivated in cancer cells." (PMID 25136623, 2014). "Carrying an inherited mutation in the BRCA1 or BRCA2 gene increases a woman's lifetime risk of developing breast, ovarian and other cancers." (PMID 24698998, 2014). "Median age of diagnosis was 50 years for the non-BRCA1/2 patients compared to 42 years (BRCA1) and 43.5 years (BRCA2) for mutation carriers and 61 years for sporadic cancer patients." (PMID 24479546, 2014). "At subsequent appointments with the familial cancer clinic, the son and two daughters were identified to have inherited the BRCA2 mutation." (PMID 24963353, 2014). "Young women who have been identified as carrying a deleterious mutation in BRCA1 or BRCA2 face a unique set of challenges related to managing cancer risk during a demographically-dense stage of life." (PMID 24586286, 2014). "Our findings provide fresh insight into the mechanism by which the HMG20b-BRCA2 complex controls mitotic cell division, and implicate heterozygous HMG20b mutations affecting cytokinesis regulation in the genesis of human cancers." (PMID 25486196, 2014). "Collectively, these data suggest that cancers arising in germline BRCA2 mutation carriers frequently fail to exhibit loss of the wildtype allele, and that failure to exhibit LOH occurs in BRCA2‐mutant cancers from several different tissues." (PMID 24268522, 2014). "Mitochondrial dysfunction and loss of BRCA2 in sporadic cancer lead to nuclear genomic instability, cumulative mutations, and tumor progression but also enhance cancer cells sensitivity to apoptosis induced by PARP inhibitors." (PMID 25136623, 2014). "Women with germ-line heterozygous mutations in either BRCA1 or BRCA2 genes has been shown to be at increased risk of developing breast, ovarian and also other cancers." (PMID 25594033, 2014). "Specifically, BRCA2 N372H polymorphism was shown to confer 13%, 7%, and 13% increases in cancer risk under the homozygous, dominant and recessive models, respectively." (PMID 25348552, 2014). "Pooled analysis yielded a statistically significant association between BRCA2 N372H variant and overall cancer risk." (PMID 25348552, 2014). "The results indicated that the BRCA2 N372H variant was significantly associated with an increased risk of overall cancer (dominant model: OR = 1.07, 95% CI = 1.01–1.13; recessive model: OR = 1.12, 95% CI = 1.02–1.23)." (PMID 25348552, 2014). "Heterozygous mutation of BRCA1 or BRCA2 causes hereditary breast and ovarian cancer syndromes at an early age and increases the chance of bilateral cancers." (PMID 24317580, 2014).
cancer (continued). "Humans who carry heterozygous germline mutations in the BRCA2 gene are highly predisposed to cancers of the breast, ovary, pancreas, prostate and other tissues." (PMID 24268522, 2014). "In this comprehensive meta-analysis for the association between BRCA2 N372H polymorphism and cancer risk, 46 studies with a total of 36299 cases and 48483 controls were included." (PMID 25348552, 2014). "In general, these studies found that BRCA1 and BRCA2 germline-mutated cancers harbored a greater number of break points and hence copy number changes." (PMID 25093514, 2014). "It has been widely believed that loss of the second, wild‐type BRCA2 allele in nascent cancer cells (termed ‘loss of heterozygosity’ or LOH) is necessary for the emergence of tumours in germline mutation carriers." (PMID 24268522, 2014). "Genomic instability is thought to be a significant factor in human carcinogenesis, and germline BRCA2 mutation is linked to an increased mutation rate in Brca2-mutant mice and in BRCA2-associated human cancer." (PMID 24489863, 2014). "Well-designed and large-scale studies are needed to substantiate the association between BRCA2 N372H polymorphism and cancer risk." (PMID 25348552, 2014). "MK-4827, also known as niraparib, is a novel 2-phenyl-2H-indazole-7-carboxamide PARP inhibitor that displayed anti-proliferation activities against BRCA1- and BRCA2-deficient cancer cells in vitro." (PMID 24795863, 2014). "BRCA1- or BRCA2-deficient cells are sensitive to siRNA-mediated knockdown or chemical inhibition of PARP, leading to the clinical testing of PARP inhibitors as potential anti-cancer drugs in BRCA1- or BRCA2-deficient cancers." (PMID 24792170, 2014). "Le cancer du sein chez l ́homme dû à une mutation du BRCA2 survient plus tôt et avec un pronostic plus sombre." (PMID 24711870, 2013). "More specifically, a strong correlation between increased genomic instability, DNA repair defects, and cancer predisposition has been documented in cells isolated from individuals carrying germ line mutations in BRCA1 or BRCA2 genes." (PMID 23675572, 2013). "Uncovering other genes that become mutated subsequent to BRCA1/BRCA2 inactivation during cancer development will be helpful for more effective treatments." (PMID 23522120, 2013). "The tumor suppressor gene breast cancer susceptibility gene 2 (BRCA2) is frequently mutated or epigenetically repressed in human cancer and has a significant role in the homologous recombination (HR) of DNA double-strand breaks (DSBs)." (PMID 23833673, 2013). "Increased sensitivity to DNA-damaging anti-cancer drugs has been associated with BRCA1 or BRCA2 functional loss involving germline mutations or epigenetic changes." (PMID 23964347, 2013). "Prediction of SL interactions a priori also has been successful in identifying therapeutic targets, as exemplified by the identification of poly-ADP-ribose polymerase (PARP) as a therapeutic target for cancers with BRCA1 or BRCA2 mutations." (PMID 23390603, 2013). "A single nucleotide polymorphism in the 5′-untranslated region (5′-UTR) of RAD51 (a G to C substitution at position 135, the G/C polymorphism) can influence cancer risk among BRCA1/BRCA2 mutation carriers." (PMID 24040396, 2013). "Conversely, nPARP expression was significantly increased in cancers with BRCA1 or BRCA2 mutations compared to sporadic tumours." (PMID 24191908, 2013). "Mutations in the BRCA2 tumor suppressor protein leave individuals susceptible to breast, ovarian and other cancers." (PMID 24627786, 2013). "One study indicated that BLBC associated with BRCA1 gene inactivation expresses lower levels of p16 than carcinomas associated with inactivation of BRCA2, which were more frequently ER positive." (PMID 23717338, 2013).
cancer (continued). "Haploinsufficiency in BRCA2+/- cells has been shown to affect DNA damage repair of breaks induced by γ-irradiation and mitomycin C which can contribute to cancer predisposition in mutation carrier families." (PMID 22513257, 2012). "The KRAS-variant predicts a significant increased risk of developing a third independent cancer in all double primary patients (p<0.01), which was largely due to increased risk for uninformative patients (p<0.005) and also possibly BRCA2 patients (p<0.05)." (PMID 22662244, 2012). "Preclinical studies have demonstrated that cancer cells with defective HR repair caused by either BRCA1 or BRCA2 inactivating mutations, display exquisite sensitivity to PARP inhibitors." (PMID 23251575, 2012). "Cancers with BRCA1 or BRCA2 mutations exhibited a characteristic combination of substitution mutation signatures and a distinctive profile of deletions." (PMID 22608084, 2012). "Recently PARP inhibitors have been shown to be highly effective in tumors with an underlying susceptibility to DNA damage, such as BRCA1 and BRCA2 mutation related cancers." (PMID 22768044, 2012). "The inhibition of PARP alone is not sufficient to kill normal cells, but it results in an accumulation of lesions in the DNA and in repair-deficient BRCA1 or BRCA2 mutated cancers, these factors combined cause cell death." (PMID 24970153, 2012). "The present analysis methods for determining the BRCA2 base sequence and for detecting BRCA2 splicing variants and the BRCA2 ORF consensus sequence are useful for better understanding the relationship between canine BRCA2 mutation status and cancer risk." (PMID 22471976, 2012). "Treatments with Poly(adenosine diphosphate ribose) polymerase (PARP) inhibitors have offered patients carrying cancers with mutated BRCA1 or BRCA2 genes a new and in many cases effective option for disease control." (PMID 24970153, 2012). "Recent work has indicated that HR defects exist in various cancer cells, with inherited mutations in HR-promoting factors such as BRCA1 and BRCA2 leading to elevated cancer predisposition." (PMID 22893507, 2012). "In the long term it is likely that diagnostic laboratories will routinely use next generation sequencing (NGS) to identify mutations in BRCA2 and other relevant genes in the diagnostic biopsy when the patient initially presents with cancer." (PMID 23284877, 2012). "All tumors derived from BRCA1 or BRCA2 germline mutation carriers showed loss of wild-type haplotypes at 17q21 or 13q12, respectively, as expected of recessive cancer genes." (PMID 22608084, 2012). "Nine percent of these cancers show alterations in BRCA1 gene while 3 percent have shown BRCA2 variants." (PMID 21559243, 2011). "Epidemiological study of BRCA1 and BRCA2 mutation carriers (EMBRACE): EMBRACE is supported by Cancer Research UK Grants C1287/A10118 and C1287/A11990." (PMID 21427728, 2011). "Perhaps the strongest evidence for the role of DNA repair in resistance to cisplatin is the somatic reversion of BRCA1 and BRCA2 mutations to DNA repair proficient proteins in chemotherapy-resistant cancers, initially treatment-sensitive." (PMID 21679440, 2011). "Out of these SNPs, several occur in genes associated with behavior (Scn10A), metabolism (Ppgca1b), cancer (Brca2), and immune response (Map3k1, OAS2, IL18R1)." (PMID 21668978, 2011). "Although mutations of BRCA2 are involved in only a small percentage of human cancers, the germline BRCA2 mutations are of high penetrance in malignant neoplasms." (PMID 21966279, 2011). "Individuals heterozygous for loss of function mutations in the tumour suppressor gene BRCA2 are highly predisposed to a range of different cancers." (PMID 21750719, 2011).
cancer (continued). "Amino acids 1 to 40 interact with PALB2, and sequence variants in this region have been shown to have effects on the PALB2 and BRCA2 interaction and thus are suspected to have a role in cancer predisposition." (PMID 21356067, 2011). "If PARP activity is lost by using specific inhibitors, the formation of DNA lesions increases and, when this event is contemporary with deficiency of BRCA1 or BRCA2 proteins, a “synthetic lethality” situation occurs for the cancer cells." (PMID 21926946, 2011). "After more than a decade of clinical testing for mutations of BRCA1 and BRCA2, there remains considerable uncertainty regarding cancer risks associated with inherited mutations of these genes." (PMID 21060860, 2010). "Clinically important mutations in BRCA1 and BRCA2 genes and cancer incidence in relatives from Estonia." (PMID 20380699, 2010). "Members of hereditary breast/ovarian cancer (HBOC) families who have been affected by cancer are offered testing for mutations in the BRCA1 and BRCA2 cancer predisposition genes with the hope of identifying the cause of the family's cancers." (PMID 20180951, 2010). "They do, however, share with the women in families in which a BRCA1 or BRCA2 mutation has been identified a fear of a new cancer and the overwhelming experience that comes along with that cancer." (PMID 20180951, 2010). "We next analyzed the incidence of cancer in relatives of those individuals identified as carrying BRCA1or BRCA2 mutations." (PMID 20380699, 2010). "It is thought that the BRCA1 and BRCA2 proteins function in many tissues to repair DNA damage, so the limited cancer causation to breast and ovary remains a mystery." (PMID 20111735, 2010). "The demonstration that inhibition of PARP activity provided specific anti-tumor activity toward BRCA2 deficient tumors was the first time DNA repair had been exploited to kill a cancer." (PMID 21037379, 2010). "Inherited susceptibility genes, BRCA1 and BRCA2, are considered in breast, ovarian and other common cancers etiology." (PMID 20579331, 2010). "We then studied a second validation data set of men with germline mutations in the BRCA2 gene from a cancer genetics clinic and assessed their survival to confirm our results in a different UK data set of male BRCA2 mutation carriers with PrCa." (PMID 20736950, 2010). "Combined with our data, it appears that loss of BRCA1 or BRCA2 function results in a more proliferative luminal cancer when an ER+ cancer develops." (PMID 21080930, 2010). "The uptake for additional psychological support was significantly higher in women with a proven BRCA1 or BRCA2 mutation (91% vs 67%; p = 0.03), and tended to be higher in women with experience of death due to cancer of a sister (23% vs 2%; p = 0.07)." (PMID 19338651, 2009). "Although mutation of BRCA2 itself is involved in only a small population of human cancer, the germline BRCA2 mutations are highly penetrative to cancer." (PMID 19653894, 2009). "As expected, there was a significant association between the presence of BRCA1 or BRCA2 mutations and the occurrence of cancer; p<0.0001." (PMID 19329713, 2009). "Nevertheless, assessment of the likelihood of carrying deleterious mutations in BRCA1 or BRCA2 genes among patients who present high-risk cancer evaluation clinics will provide more accurate guidance to women and families about considering genetic testing." (PMID 19619314, 2009). "Epidemiological study of BRCA1 and BRCA2 mutation carriers (EMBRACE): EMBRACE is supported by Cancer Research UK Grants C1287/A10118 and C1287/A8874." (PMID 19920816, 2009). "Germ-line mutations in the BRCA1 and BRCA2 genes confer a high lifetime risk of developing breast and other cancers." (PMID 19920816, 2009).
cancer (continued). "Our findings further confirm that mutation frequency for BRCA1 and BRCA2 as cancer susceptibility genes for breast-ovarian carcinoma needs to be evaluated in each distinct geographical area." (PMID 19619314, 2009). "The BRCA2 gene plays critical roles in the maintenance of genomic stability by regulating homologous recombination, and BRCA2 defects are associated with predisposition to various human cancer." (PMID 19653894, 2009). "This is in agreement with data showing that mutations in the BRCA1 gene are rarely linked to cancer at sites other than breast and ovary, while mutations in the BRCA2 gene are." (PMID 19329713, 2009). "We and others have recently shown that carcinomas from patients with inherited frameshift mutations in BRCA1 or BRCA2 exposed to chemotherapy can acquire secondary mutations that restore the reading frame of BRCA1 or BRCA2, resulting in platinum resistance." (PMID 19602291, 2009). "We apply the method to a tumor suppressor gene, BRCA2, whose loss of function is important to cancer susceptibility." (PMID 19043619, 2008). "It therefore seems that only in those rare families with FA cases due to BRCA2 or FANCJ/FANCN mutations is cancer risk in heterozygotes a salient factor." (PMID 18786261, 2008). "This shows a substantial effect of cancer burden for BRCA2 with high-risk families (scores above 20 points) having a much lower proportion of positive predictive tests after 50 years." (PMID 18513387, 2008). "The spectrum of cancers associated with BRCA2 mutations likely includes other cancers as well, such as pancreatic, prostate, stomach, melanoma, gallbladder, and bile duct cancers." (PMID 19043619, 2008). "We reviewed 385 unrelated families (223 with BRCA1 and 162 with BRCA2 mutations) ascertained through two regional cancer genetics services." (PMID 18513387, 2008). "Population-based studies have shown that mutations in BRCA1 and BRCA2 confer an increased risk of breast, ovarian and other cancers." (PMID 19102775, 2008). "Future directions for our group include studying more VUS in BRCA2 and in other cancer-susceptibility genes." (PMID 19043619, 2008). "BRCA1 and BRCA2 mutations are associated with increased risk of cancer at several sites other than female breast and ovary." (PMID 18349832, 2008). "It is generally thought that BRCA2 mutations primarily affect women, but men with mutations are also at elevated cancer risk." (PMID 18577985, 2008). "We have presented a new computational approach for analyzing the impact of missense changes in the DNA-binding domains of the cancer susceptibility protein BRCA2 that uses information from protein sequence, structure, and sequence conservation." (PMID 19043619, 2008). "Germline mutations in BRCA1 (MIM 113705) and BRCA2 (MIM 600185) genes account for cancer predisposition in majority of families with BC recurrence." (PMID 17640379, 2007). "The increased chance of developing BC and PC in individuals with either the BRCA1 or BRCA2 mutation is consistent with the increased bcl-2 caused by the elimination of PRB being partly responsible for the increased incidence of cancer." (PMID 17678531, 2007). "During tumorigenesis, mismatch repair deficient cancer cells evidently experiment extensively with BRCA2 mutations, perhaps as a consequence of the high number of repetitive sequences in the BRCA2 gene in combination with locus susceptibility to mutation." (PMID 16417627, 2006). "We found heterozygous frameshift mutations in the BRCA2 gene to be present in 47% of gastrointestinal MSI cancer cell lines, a much higher percentage than previously reported." (PMID 16417627, 2006). "We analyzed gastrointestinal MSI cancers by whole gene BRCA2 sequencing, finding heterozygous truncating mutations in seven (47%) of 15 patients." (PMID 16417627, 2006). "It has been shown that gross chromosomal changes are more likely to occur in cancers occurring in individuals with germline mutations in BRCA1 and BRCA2 compared with sporadic cancers." (PMID 16404418, 2006).